TRIB3 (tribbles pseudokinase 3)
Diseases named in the same sentence as TRIB3 in open-access papers (continued):
Sharing a sentence is not in itself a finding about the gene and the disease.
breast carcinoma (continued). "Surprisingly, in the same group of breast cancer patients we found that TRIB3 protein expression had an opposite relation with prognosis." (PMID 23185332, 2012). "For this we analyzed protein degradation and mRNA translation rates of TRIB3 in breast cancer cell lines under normoxic and hypoxic conditions." (PMID 23185332, 2012). "The discrepancies between TRIB3 mRNA and protein and their opposing relation with breast cancer prognosis spurred us to investigate the regulatory mechanisms involved in TRIB3 translation." (PMID 23185332, 2012). "In this study, we investigated this discrepancy between TRIB3 mRNA and protein in human breast cancer." (PMID 23185332, 2012). "In breast tumor xenografts and human breast cancer tissues TRIB3 co-localized with the hypoxic cell marker pimonidazole." (PMID 21864376, 2011). "Next, we assessed TRIB3 staining in breast cancer tissue from three patients that had received pimonidazole prior to biopsy." (PMID 21864376, 2011). "TRIB3 is expressed in hypoxic areas of both breast cancer xenografts and human breast tumor tissues." (PMID 21864376, 2011). "We found that TRIB3 up-regulation after hypoxia, ER stress and nutrient starvation also holds true for breast cancer cells and is HIF-1 independent and UPR dependent." (PMID 21864376, 2011). "Here, we show that TRIB3 expression can independently predict disease outcome in human breast cancer patients." (PMID 21864376, 2011). "A relation of TRIB3 with hypoxia was seen by the co-localization with the hypoxia marker pimonidazole in both breast cancer xenografts and human breast tumor tissue." (PMID 21864376, 2011). "Breast cancer patients with low, intermediate or high TRIB3 expression exhibited a mean disease free survival (DFS) of 80 (95% confidence interval [CI] = 74 to 86), 74 (CI = 67 to 81), and 63 (CI = 55 to 71) months respectively (P = .002, Mantel-Cox log-rank)." (PMID 21864376, 2011). "Moreover, TRIB3 is considered a potential oncogene in solid tumor cells, such as colorectal and breast cancers." (PMID 39910904, 2025). "In breast cancer, TRIB3 supports cell stemness by regulation of SOX2 transcription." (PMID 37189176, 2023). "It has been found that TRIB3 is positively related to breast cancer stemness and development." (PMID 37732314, 2023). "In this study, we show that TRIB3 is able to regulate PPARγ expression in breast cancer cells." (PMID 36142452, 2022). "Recent research studies evidenced that the expression of TRIB3 could be upregulated in a number of cancers, such as breast cancer, colorectal cancer, and lung cancer." (PMID 36120545, 2022). "Given the importance of mitochondrial amino acid metabolism for histone methylation, by altering mitochondrial function, TRIB3 may affect gene regulation in breast cancer through a second, more indirect mechanism." (PMID 36142452, 2022). "By suppressing FOXO1 degradation and increasing SOX2 transcription, TRIB3 can help breast cancer." (PMID 36245981, 2022). "In this study we describe TRIB3 as a regulator of PPARγ expression in breast cancer cells, and we hypothesize that TRIB3 achieves this through binding to the WRAD complex and regulating the H3K4me3 mark around the PPARγ locus." (PMID 36142452, 2022). "Consequently, the overexpression of TRIB3 blunts the antiproliferative effect of PPARγ ligands in breast cancer cells, while reduced TRIB3 expression gives the opposite effect." (PMID 36142452, 2022). "Indeed, we found that TRIB3 repressed gene transcription when tethered to DNA in breast cancer cells." (PMID 34944947, 2021). "However, the role of TRIB3 in luminal breast cancer, the most frequent BC subtype which often harbors alterations in the PI3K/AKT pathway, remains to be explored." (PMID 34771470, 2021). "TRIB3 negatively regulated the stability of HER2 in luminal B breast cancer cell lines." (PMID 34771470, 2021).
breast carcinoma (continued). "Studies have shown that the high expression of TRIB3 in breast cancer and oral squamous cell carcinoma indicated a better prognosis, but whether it can affect GC prognosis has not been confirmed." (PMID 34957220, 2021). "In this work, the analysis of TRIB3 expression in a tissue microarray that was generated with samples from patients of luminal breast cancer revealed a clear correlation between high TRIB3 expression and higher DFS in this cohort that contained a majority of HER2− tumors." (PMID 34771470, 2021). "Importantly, analysis of samples from luminal breast cancer patients identified TRIB3 as a potential biomarker of good prognosis and response to therapy in this breast cancer subtype." (PMID 34771470, 2021). "Arid5a under IL6 signaling binds to the upstream region of a lncRNA, AU021063, and transcriptionally upregulates the expression of this noncoding RNA, which further leads to the enhanced invasion and metastasis of breast cancer cells in mice by stabilizing the tribbles homolog 3 (Trib3) protein." (PMID 35126382, 2021). "Thus, our observations support the notion that enhanced expression of TRIB3 promotes the proliferation of luminal A while driving the opposite effect in luminal B (HER2+) breast cancer cell lines." (PMID 34771470, 2021). "Considering the previous observations, we wondered whether TRIB3 expression had a differential predictive value in luminal A and B breast cancer." (PMID 34771470, 2021). "Other studies confirmed that the expression of TRIB3 is greater in solid tumors such as colorectal cancer, breast cancer, lung cancer, ovarian cancer, melanoma, liver cancer, and leukemia, suggesting that TRIB3 is a potential target for cancer treatment." (PMID 33841505, 2021). "Having developed a robust AP–MS workflow to identify the interaction partners of Tribbles proteins, we wished to address the different roles of TRIB1 and TRIB3 in breast cancer, where high levels of both proteins have been reported to be associated with poor prognosis and lower survival rates." (PMID 34944947, 2021). "For this we generated inducible TRIB1-tGFP and TRIB3-tGFP stable cell lines in the breast cancer cell line MCF7, a model for luminal A breast cancer, allowing immediate short-term overexpression of TRIB1 and -3, as well as control over the amount of protein being overexpressed." (PMID 34944947, 2021). "We also investigated the relationship between TRIB3 mRNA levels and disease-free survival (DFS) in breast cancer patients using the Cancertool platform and found that although several studies revealed a correlation between high TRIB3 mRNA levels and worse prognosis results were variable." (PMID 34771470, 2021). "Thus, this work provides a proof-of-concept for directly targeting BCSCs against breast cancer through inhibition of the TRIB3/AKT1 interaction." (PMID 31844113, 2019). "Moreover, we found that TRIB3, as well as other markers of the autophagy-mediated cell death pathway, are upregulated in vivo upon GA administration to mice bearing breast cancer xenografts." (PMID 31578236, 2019). "However, TRIB3 has been reported to be overexpressed in several cancer types, such as breast cancer and colorectal cancer." (PMID 30678233, 2019). "Thus, TRIB3 consistently reduced the phosphorylation of AKT1, a kinase that can interact with FOXO1 25, indicating that the AKT-FOXO1 interaction plays a critical role in TRIB3-enhanced breast cancer stemness." (PMID 31844113, 2019). "Our data suggest that TRIB3 expression may serve as a biomarker for prediction of radiation response in breast cancer patients and targeting TRIB3 could be a potential strategy for developing future breast cancer therapy." (PMID 30678233, 2019). "Furthermore, higher TRIB3 and ULK1 expression is associated with a poor prognosis in breast cancer while higher LAMP3 expression has been associated with lymph node positivity and hormone receptor negative breast cancers." (PMID 30248920, 2018).
breast carcinoma (continued). "We could not find any effect of inhibiting proteasomal degradation on the TRIB3 protein levels in breast cancer cells both during normoxia and hypoxia." (PMID 23185332, 2012). "We could confirm that the only so far known TRIB3 specific micro RNA (miRNA-24) was upregulated during hypoxia in breast cancer cells." (PMID 23185332, 2012). "Next, we assessed whether an inverse correlation exists between miRNA-24 and TRIB3 mRNA or protein levels in breast cancer patients." (PMID 23185332, 2012). "Thus, the expression of miRNA-24 does not explain the difference between mRNA and protein expression of TRIB3 in this cohort of breast cancer patients." (PMID 23185332, 2012). "Furthermore, we studied TRIB3 expression regulation in cell lines, xenografts tissues and human breast cancer material using Reverse transcriptase, quantitative polymerase chain reaction (RT-qPCR) and immunohistochemical staining." (PMID 21864376, 2011). "This apparent involvement of TRIB3 in tumor cell proliferation and/or survival and growth factor receptor signaling cascades combined with its role in hypoxia and cell stress pathways originally spurred us to investigate its role in breast cancer progression." (PMID 21864376, 2011). "TRIB3 expression was increased in breast cancer cells after 24 hours of anoxia (P < 0.05)." (PMID 21864376, 2011). "We hypothesized that TRIB3 could be relevant for breast cancer prognosis, because in breast cancer, several ER stress, UPR, and/or hypoxia-associated markers have been found to be related to prognosis." (PMID 21864376, 2011). "Here, we find that TRIB3 is associated with poor prognosis of breast cancer patients, independent of other clinicopathological characteristics." (PMID 21864376, 2011). "Finally, we determined the effect of TRIB3 knockdown on the hypoxia response of breast cancer cells." (PMID 21864376, 2011). "In conclusion, our data implicate TRIB3 in epigenetic gene regulation and suggest that expression levels of this pseudokinase may serve as a predictor of successful experimental treatments with PPARγ ligands in breast cancer." (PMID 36142452, 2022). "Thus, the molecular alterations that are characteristic of each breast cancer subtype may directly impact on the capacity of TRIB3 to regulate this and other oncogenic signaling pathways." (PMID 34771470, 2021). "From these results, it is tempting to speculate that the strategies that are aimed at driving TRIB3 upregulation could act as sensitizers to other therapies and therefore be beneficial in the treatment of luminal breast cancer patients when used in combination with current anticancer treatments." (PMID 34771470, 2021). "In this study we found that TRIB3 and AKT interact with each other at a similar extent in both types of luminal breast cancer cell lines suggesting that the mechanisms that determine this dual role of TRIB3 in the regulation of AKT and AKT downstream targets may rely on additional factors." (PMID 34771470, 2021). "In addition, we found that the expression of TRIB3 were of diagnostic value for GC, while FABP1 were of diagnostic value for both GC and EGC, and as suggested by the previous research results in renal cancer and breast cancer." (PMID 34957220, 2021). "In addition, TRIB3 overexpression correlated with a poor prognosis of breast cancer patients." (PMID 29757932, 2018). "Furthermore, we used a patient cohort to investigate if miRNA-24 could mediate translational inhibition of TRIB3 mRNA, and whether the level of miRNA-24 itself has prognostic value in breast cancer." (PMID 23185332, 2012). "Thus, the relation of TRIB3 protein with a good prognosis in breast cancer patients could be due to its role in hypoxia-induced cell death." (PMID 23185332, 2012). "Therefore, we wondered whether TRIB3 protein was in breast cancer cells as unstable as suggested before." (PMID 23185332, 2012).
breast carcinoma (continued). "In addition, we determined if TRIB3 expression could be induced in breast cancer cells by a variety of stressors, and we assessed the expression and localization of TRIB3 in breast cancer xenografts and patient tissues." (PMID 21864376, 2011). "Next, to assess whether the oxygen dependence of TRIB3 expression could also be observed in tissues, frozen sections of MDA-MB-231 human breast cancer cell xenografts grown on nude mice were triple stained with fluorescent anti-pimonidazole, anti-TRIB3, and anti-endothelial antibodies." (PMID 21864376, 2011). "Finally, knockdown of TRIB3 revealed an effect on hypoxia response of breast cancer cells." (PMID 21864376, 2011). "TRIB3 can regulate the PI3K / AKT / mTOR pathway to affect cellular energy metabolism, which has been confirmed in liver cancer, breast cancer, and oropharyngeal cancer." (PMID 39869954, 2025). "TRIB3 has been reported to mediate breast cancer (BC) proliferation and metastasis by interacting with AKT1, and blocking the interaction between TRIB3 and AKT1 can inhibit the progression of BC." (PMID 39881875, 2024). "TRIB3 was identified as a master regulator of JAG1 (Jagged canonical Notch ligand 1) gene expression, and Notch activation in breast cancer." (PMID 33920424, 2021). "Similar effects of TRIB3 onto MAPK-dependent pro-survival and pro-migratory effects were reported in renal cell carcinoma, or breast cancer, completed with interactions with TGFβ pathway." (PMID 33920424, 2021). "To further validate the role of TRIB3 as a transcriptional repressor we tested the Gal4DBD-TRIB3 fusion protein for HEK293T cells, and also detected reduced transcriptional activity in these MCF7 breast cancer cells." (PMID 34944947, 2021). "In the present work we found that TRIB3 differentially regulates the proliferation and the activation of the PI3K/AKT pathway of breast cancer cell lines depending on their HER2 status." (PMID 34771470, 2021). "In contrast, previous analyses have demonstrated that the TRIB3-mediated inhibition of the protein kinase AKT inhibited tumor growth in different tumor models, including breast cancer cell lines." (PMID 34771470, 2021). "Recently, TRIB3 was reported to regulate the β-catenin pathway in colorectal cancer and to suppress forkhead box protein O1 (FOXO1) phosphorylation in breast cancer by helping to maintain cancer stem cells (CSCs)." (PMID 33334065, 2020). "Disturbing the TRIB3-AKT interaction suppresses BCSCs by accelerating FOXO1 degradation and reducing SOX2 expression in mouse models of breast cancer." (PMID 31844113, 2019). "The fact that the TRIB3-AKT1 interaction prohibits the AKT1-FOXO1 interaction provides an opportunity to modulate the effects of the niche-enriched stress protein TRIB3, which indeed shows enhanced expression adjacent to CD68+ TAMs in breast cancer patients." (PMID 31844113, 2019). "However, the direct involvement of TRIB3 in radioresistant breast cancer cells remains unclear." (PMID 30678233, 2019). "In the current study, we systematically investigated SOX7-mediated transcription in breast cancer MDA-MB-231 cells, which have an undetectable endogenous SOX7 expression, and discovered TRIB3 and MTHFD2 as its repressed genes." (PMID 29757932, 2018). "Our results presented here show that TRIB3 could be involved in the hypoxia response of breast cancer cells; it is induced by cell stressors including hypoxia, ER stress, and nutrient starvation in breast cancer cells, which is in line with earlier observations in other cell types." (PMID 21864376, 2011). "Moreover, TRIB3, which is highly expressed in prostate cancer, can be targeted by Palbociclib, a CDK4/6 inhibitor approved for the treatment of breast cancer, augmenting the response of prostate cancer cells to ferroptosis inducers." (PMID 39941896, 2025). "Interestingly, we observed that LSM4 was closely ranked with other breast cancer biomarkers, such as DPP3, CDK5, and TRIB3." (PMID 34638387, 2021).
breast carcinoma (continued). "Previous studies had shown that TRIB3 mRNA and protein levels do not always correlate in human breast cancer patient samples." (PMID 34771470, 2021). "Moreover, bioinformatic analyses revealed the existence of a strong correlation between TRIB3 and HER2 mRNA levels in a wide panel of human breast cancer cell lines as well as in the TGCA BC database." (PMID 34771470, 2021). "Knockdown of HIF-1α did not alter the anoxia induction of TRIB3 expression at any time point, which is in line with our results in breast cancer cells after CoCl2 incubation." (PMID 21864376, 2011). "In contrast, we had previously shown that TRIB3-mediated inhibition of AKT and the subsequent activation of FOXO transcription factors reduces cell proliferation and survival and inhibits tumor growth in different tumor models, including breast cancer cell lines." (PMID 34771470, 2021). "We have shown the ability of TRIB3 to function as a transcriptional repressor as we looked at the similarities and differences between TRIB1 and -3 in breast cancer cells, finding new interactors that might help to understand better the function of these proteins in breast cancer pathology." (PMID 34944947, 2021). "TRIB3 expression showed no stage differences among a variety of breast cancer patients." (PMID 31844113, 2019). "However, miRNA-24 levels did not correlate with either mRNA or protein expression of TRIB3 in breast cancer patients." (PMID 23185332, 2012). "Thus, proteosomal degradation is not involved in the apparent strict regulation of TRIB3 protein levels in breast cancer cells." (PMID 23185332, 2012). "Furthermore, our results indicate that this effect of TRIB3 genetic manipulation is mediated by changes in the activity of the AKT/FOXO axis, suggesting that this pseudokinase regulates the AKT pathway differently in luminal A and luminal B breast cancer cell lines." (PMID 34771470, 2021). "TRIB3 is universally highly expressed in HMLER and eight distinct breast cancer epithelial cell lines but not in human mammary epithelial cells (HMLEs)." (PMID 31844113, 2019). "To test the effect of different stresses on TRIB3 mRNA expression we used the estrogen receptor positive MCF7 and estrogen receptor negative MDA-MB-231 breast cancer cells." (PMID 21864376, 2011). "We have examined possible changes in levels of GRP78 and other markers of ER stress in breast cancer cells treated with TAIII, An induction in levels of GRP78 and TRIB3 was observed in MDAMB231 cells but not in BT474 cells, indicating a weak or possibly atypical ER stress response in the latter." (PMID 19789631, 2009).